IL10 (interleukin 10)
Diseases named in the same sentence as IL10 in open-access papers (continued):
Sharing a sentence is not in itself a finding about the gene and the disease.
periodontal disease (77 papers, 2010 to 2025). "The identification of IL-10-producing B cells and evidence for genetic polymorphisms affecting IL-10 expression add further layers to its immunoregulatory significance in periodontal disease." (PMID 41289041, 2025). "This association is attributed to IL-10’s role in modulating the immune response and influencing the inflammatory pathways involved in periodontal disease." (PMID 39336814, 2024). "The interactions of IL-10, IL-12, and IL-18 are implicated in the progression of periodontal disease." (PMID 39080003, 2024). "The severity of periodontal disease has been associated with reduced serum levels of the anti-inflammatory cytokine IL-10 in contrast to an increase in inflammatory biomarkers." (PMID 38033572, 2023). "IL-10 is an anti-inflammatory cytokine, whose deficiency or impaired function was suggested as a potential factor increasing susceptibility to periodontal disease." (PMID 35454140, 2022). "Conversely, the periodontal diseases are correlated to associated to a Th2 cell-mediated and an overexpression of the IL-4, IL-5, IL-6, and IL-10 mediators." (PMID 35735643, 2022). "Individuals with CP have higher risk to develop periodontal disease due to reduced salivary flow rate, increased salivary osmolality rate and elevated TNFα, IL-10, IL-6 compared to DS." (PMID 32509226, 2020). "Individuals with cerebral palsy present higher risk to develop periodontal disease due to the reduced salivary flow rate, increased salivary osmolality rate and elevated levels of TNFα, IL-10, IL-6 compared to individuals with individuals with Down syndrome." (PMID 32509226, 2020). "Periodontal disease susceptibility in the CP group was evaluated with logistic regression analysis of IL-10 AA genotypes after adjustment of age and sex." (PMID 29489938, 2018). "Gene polymorphisms have been investigated as possible markers of increased susceptibility to periodontal diseases: IL-1, IL-4, IL-10; TNF-α; Fcγ receptor; human leukocyte antigen; vitamin D receptor; and N-formyl peptide receptor." (PMID 20170537, 2010). "Next we measured levels of the immunoregulatory/anti-inflammatory cytokine IL-10, a key molecule associated with periodontal disease and host response to Pg." (PMID 21114831, 2010). "Considering the modulatory role of CTRP-1 in inflammation, analyzing its association with inflammatory mediators like TNF-α and IL-10 in periodontal disease may offer important perspectives on disease progression and potential interventions." (PMID 40542868, 2025). "Similarly, Allium sativum (garlic) extract was shown to elevate IL-10 and IL-13 levels, providing protective effects against alveolar bone loss and promoting anti-inflammatory responses in periodontal disease." (PMID 39539670, 2024). "Consequently, the IL-10 polymorphisms seem to be of high clinical relevance by ethnicity and would be a useful marker to identify patients who are at higher risk for periodontal disease." (PMID 35454140, 2022). "Considering that bacterial LPS is a major disease-inducing antigen in periodontal diseases, we assessed the role of Nlrp3 and Caspase-1 on the expression of the inflammation- and macrophage phenotype-associated genes Il-10, Il-12 and Tnf-α in primary bone marrow-derived macrophages." (PMID 32385413, 2020). "Some studies to analyze the SNPs in the promoter region of the IL-10 gene and its relation with periodontal disease have revealed that these polymorphisms might be associated with susceptibility to CP." (PMID 30755190, 2019). "In periodontal disease, IL-10 is thought to be associated with lower disease severity." (PMID 25587209, 2014). "A connection between anti-citrullinated protein antibodies and IL-10 polymorphisms has been discovered, indicating that IL-10 expression may confer protection against periodontal disease when anti-citrullinated protein antibodies are present in the bloodstream." (PMID 38790898, 2024).
periodontal disease (continued). "Similarly, a study showed that higher levels of IL-2, IL-6, IL-10, TNF-α, and PGE2 were detected in the serum of preterm women with periodontal disease, while the serum levels of IL-2, IL-6, and IL-10 were higher in high-risk preterm women than in low-risk preterm women." (PMID 36388896, 2022). "However, elevated levels of TNF-α, IL10, IL-6, IL-1β and IL-8 were observed in the CP group, which may increase the susceptibility and progression of periodontal disease in these individuals." (PMID 32509226, 2020). "These discrepancies highlight the versatile role of IL-10 in periodontal disease and need for further investigation." (PMID 40542868, 2025). "ROC analyses have shown that both TNF-α and IL-10 exhibit high AUC value, supporting their utility as biomarkers in periodontal disease status." (PMID 40542868, 2025). "This study aimed to evaluate levels of salivary and gingival crevicular fluid (GCF), interleukin − 1 beta (IL-1β), interleukin − 10 (IL-10), and Metrnl in periodontal disease." (PMID 39964474, 2025). "Nevertheless, the findings regarding TNF-α and IL-10 are consistent with those of prior research on inflammatory biomarkers in periodontal disease." (PMID 40542868, 2025). "The present study also provides in vivo evidence that Pg-LPS can inhibit TLR4-mediated increases in blood levels of IL-10, a cytokine thought to prevent the development of periodontal disease." (PMID 38857232, 2024). "Cytokines, including IL-1A, IL-1B, IL-10, and IL-6, released during gastrointestinal disturbances, are pivotal in driving the inflammatory response in periodontal disease." (PMID 39200318, 2024). "On the other hand, IL-10 is an anti-inflammatory cytokine that functions to reduce the severity of inflammatory response in patients with periodontal disease." (PMID 39851590, 2024). "There are limited studies that have evaluated the GCF IL-10 levels by means of the effect of NSPT+ LBT with an Nd:YAG laser on periodontal disease management." (PMID 38812655, 2024). "A number of candidate gene studies showed that IL1A, IL1B, IL4, IL6, IL10, TNFA, FcγR, VDR, TLR2, TLR4, and MMP1 were the main genes associated with periodontal disease." (PMID 36294882, 2022). "A pregnant woman with diagnosed periodontal disease had increased levels of IL-2, IL-4, IL-6, IL-10, TNF-α and INF-γ." (PMID 35055157, 2022). "In general, Tregs are known to suppress the pro-inflammatory environment of periodontal disease by promoting resolution of inflammation through IL-10 and TGF-β." (PMID 34778595, 2021). "Significantly higher levels of IL-1β, IL-6, IL-8, and IL-10 were found in constipated subjects with GB from this study, indicating an ongoing inflammatory process and the progression of periodontal disease." (PMID 33717115, 2021). "They release TGF-β and IL-10, thereby promoting resolution and preventing bone destruction in periodontal diseases through the inhibition of osteoclastogenesis." (PMID 34778595, 2021). "In this study, it was observed that in situ the expression of TNF-α was significantly decreased and the expression of IL-10 was significantly increased in BAFF blockade mice with periodontal disease." (PMID 34481478, 2021). "The role of IL-10 in the anti-inflammatory process and its key suppressive role in the pathogenesis of periodontal disease are well known." (PMID 32397555, 2020). "In periodontal diseases, IL-10 and IL-13 are involved in modulating the immune response and in the suppression of pro-inflammatory cytokines by monocytes/macrophages, respectively." (PMID 31973090, 2020). "Data in the literature are contradictory to the presence of IL10 and its variations with relation to periodontal disease." (PMID 31871458, 2019). "Interleukin-10 (IL-10) is an anti-inflammatory cytokine which has vital role in pathogenesis of periodontal diseases." (PMID 30755190, 2019).
periodontal disease (continued). "The aim of the present study is to evaluate and compare the presence of sialic acid (SA) and IL10 in the early stage (stage 1) and moderate stage (stage 2) of periodontal disease." (PMID 31871458, 2019). "The positive correlation between IL-10 and PD in the entire study group (N = 77) was surprising when the anti-inflammatory role of IL-10 in periodontal disease was considered." (PMID 29742255, 2018). "Patients with periodontal disease showed higher levels of cytokines (IL-2, IL-6, IL-10, and TNF-α) and PGE2." (PMID 30154640, 2018). "Most previous studies have focused on the analysis of ratios between pro-inflammatory and anti-inflammatory cytokines, or vice versa, in periodontal diseases, with IL1beta/IL10 and IL11/IL17 being the most evaluated." (PMID 30573746, 2018). "IL-6 and IL-10 genes have both a significant effect on the initiation of periodontal disease and increased levels of these proteins have been found in the gingival crevicular fluid of sites with periodontal destruction." (PMID 28624837, 2017). "β-glucan was also efficient in decreasing the serum levels of TNF-α in diabetic animals with periodontal disease and IL-10 levels in animals with periodontal disease." (PMID 28906456, 2017). "Our study suggests that polymorphisms in the IL-4 gene not only affect the production of the IL-4 cytokine but can influence production of several other cytokines, such as IL-10, IFNγ, IL-1β, IL-6, and TNFα, which in turn can affect periodontal disease." (PMID 25530681, 2014). "Among these inflammatory mediators, interleukin-10 (IL-10) has been considered and important contributor to the pathogenesis of periodontal diseases." (PMID 25129246, 2014). "For IL-10 and IL-1β, the mean was below the cut-off point in all periodontal disease diagnoses." (PMID 40002786, 2025). "Studies have reported elevated levels of pro-inflammatory cytokines (e.g., IL-10, IL-12, TNF-α) in e-cigarette users, which may contribute to microbiota dysbiosis and an increased risk of periodontal diseases." (PMID 40559585, 2025). "While periodontal homeostasis is maintained via proinflammatory [i.e. interleukin 1 beta (IL-1β)] and antiinflammatory (i.e. IL-10) cytokine balance, any destabilization beneficial for the proinflammatory cytokines results in periodontal disease, tissue destruction, and/or impaired healing." (PMID 38812655, 2024). "When macrophages polarize to the anti-inflammatory M2 type, they secrete IL-10 and Arg-1 anti-inflammatory factors, and IL-10, an important immunomodulatory factor, can inhibit osteoclastogenesis and play an osteoprotective role in periodontal disease." (PMID 36686380, 2023). "In this study, we included also IL-10 as an anti-inflammatory or immunosuppressive mediator that may exert potent regulatory effects on immune response in periodontal disease." (PMID 35368315, 2022). "This study aimed to determine serum and salivary levels of neutrophil gelatinase-associated lipocalin (NGAL) and evaluate NGAL correlation with key anti-interleukin 10 (IL-10) and pro-inflammatory (IL-1β) cytokines in different severities of periodontal diseases." (PMID 32997091, 2020). "The role of NGAL in periodontal disease pathogenesis, as regulated by IL-1β and IL-10, could be conjectured within the limitations of this study, as supported by the increased serum levels progressing from health to disease." (PMID 32997091, 2020). "Evidence indicates that periodontal disease with a predominant IL-10 deficit is most common on ATA/ACC haplotypes and this feature tends to be explained by epigenetic disturbances under the effect of both environmental and bacteria activity rather than congenital genetic predisposition." (PMID 32397555, 2020). "Therefore, the objective of this work was to analyze the cytokines IL-2, IL-6, IL-10, and TNF-α and inflammatory mediators such as PGE2 in pregnant patients at risk of preterm delivery and their relationships with periodontal disease." (PMID 30154640, 2018).
periodontal disease (continued). "This study aimed to evaluate the effects of β-glucan ingestion (Saccharomyces cerevisiae) on the plasmatic levels of tumor necrosis factor-α (TNF-α) and interleukin-10 (IL-10), alveolar bone loss, and pancreatic β-cell function (HOMA-BF) in diabetic rats with periodontal disease (PD)." (PMID 28906456, 2017). "Although the association between IL-6 and IL-10 with periodontal disease initiation has been supported extensively in the literature, the findings of this study can confirm the lack of effect of IL-6 and IL-10 on the resolution of periodontal inflammation." (PMID 28624837, 2017). "Tissue destruction caused by MMP-2 and MMP-9 was reduced in animals treated with 5 mg/kg AZT, indicating that IL-10 may be a protective cytokine in periodontal diseases." (PMID 24819928, 2014). "Consequently, the presence of IL-10 in the GCF of patients with periodontal disease may modulate the local immune response and have an anti-inflammatory effect." (PMID 39080003, 2024). "In addition, IL-10 has anti-inflammatory and immunosuppressive properties in periodontal disease." (PMID 39080003, 2024). "Thus, IL-10 could play a crucial role in limiting the duration and extent of inflammatory responses in periodontal disease patients." (PMID 39851590, 2024). "Moreover, IL-10 has been shown to inhibit IL-6 production by human gingival fibroblasts exposed to bacterial LPS, supporting the idea that this factor decreases inflammation in connective tissues in periodontal disease." (PMID 37508659, 2023). "The decreased monocyte chemotaxis and phagocytosis, the increased production of TNF-alpha, IL-4, IL-10 and IL-1, as well as the increased susceptibility to infections and the delayed healing response, explain the susceptibility of HIV-positive individuals to periodontal disease." (PMID 33916511, 2021). "Hence, IL-10 serves for the control of periodontal disease progression and the large diversity of its expression pattern in periodontal tissues may be affected by various micro-environment factors." (PMID 31443525, 2019). "Local delivery of exogenous IL-10 may represent a potential treatmentfor periodontal disease." (PMID 27074164, 2016). "The main problem related to periodontal disease is bone loss, which is caused by activation of lymphocyte pro-inflammatory cytokines, such as IL-1β and TNF-α, and may be mediated by significant increases in IL-10 levels." (PMID 24819928, 2014). "The C allele of VEGF, a regulator gene of angiogenesis and lymphangiogenesis, the A allele of IL-10, an anti-inflammatory gene and the GG genotype of TNF, a gene involved in both inflammation and bone remodeling, were associated with an increased risk of periodontal disease." (PMID 24274085, 2013). "The anti-inflammatory cytokine IL-10 was significantly reduced in T1DM individuals (F = 21.10 and p < 0.0001) across all periodontal disease classifications, presenting a significant decrease in healthy (p = 0.0003) and gingivitis groups (p = 0.03)." (PMID 41280935, 2025). "This study aimed to comparatively evaluate the levels of Metrnl, pro-inflammatory (IL-1β), and anti-inflammatory (IL-10) cytokines in salivary and GCF samples in the presence of periodontal disease." (PMID 39964474, 2025). "Cytokine IL-10 is an anti-inflammatory cytokine that functions to reduce inflammatory responses and can be found clinically in the GCF of patients with periodontal disease." (PMID 37623272, 2023). "Moreover, according to recent systematic reviews and meta-analyses, salivary IL-1β, IL-6, and MMP-8 are among the five promising biomarkers that have been identified as eligible candidates for the diagnosis of periodontal diseases; while IL-10 may have a strong regulatory effect on immune responses." (PMID 35368315, 2022). "The biomarkers showing elevated levels in the baseline saliva of patients with periodontal disease were IL-1β, IL-4, IL-6, MMP-8, and TIMP-2, while the control group showed high levels of TNF-a, IL-10, IL-17, and IL-32." (PMID 33383828, 2020).
periodontal disease (continued). "Previous studies have reported different results regarding salivary concentrations and GCF total amount of IL-10, such as increased, no differ, and decreased in periodontal diseases." (PMID 39964474, 2025). "Some studies report that GCF total amount of IL-10 increase, decrease or no differ in periodontal disease compared to periodontally healthy controls." (PMID 39964474, 2025). "To date, no studies have examined the relationship between the IL-18/IL-10 ratio and periodontal diseases." (PMID 39080003, 2024). "Biomarkers showing high levels in periodontal disease were salivary IL-1β, IL-4, IL-6, MMP-8, and tissue inhibitor of matrix metalloproteinases (TIMP)-2, and those in the controls were tumor necrosis factor (TNF)-α, IL-10, IL-17, and IL-32." (PMID 33383828, 2020). "Treatment with β-glucans reduced the TNF-α blood levels in diabetic animals with periodontal disease and IL-10 levels in diabetic and nondiabetic animals with periodontal disease (p < 0.05)." (PMID 28906456, 2017). "The consistent findings of reduced levels of IL-10 in non-smokers demonstrate that IL-10 may elicit a dysregulated immune response to periodontal disease progression in smokers." (PMID 38627806, 2024). "Moreover, it is possible that the expression of IL-6 and IL-10 can alter the levels of other cytokines or inflammatory factors that play a significant role only in the initiation of the inflammatory response and not in the healing process after treatment of periodontal disease." (PMID 28624837, 2017).